E2F1 (E2F transcription factor 1)
Diseases named in the same sentence as E2F1 in open-access papers (continued):
Sharing a sentence is not in itself a finding about the gene and the disease.
tumor (continued). "In E2f1 knockout mice, thymocytes revealed low levels of apoptosis and the animals had a high frequency of spontaneous tumor formation from different tissues." (PMID 21637599, 2010). "Even though, the roles of E2F-1 in tumor progression have been extensively investigated, however, to date, little is known about its function relevant to angiogenesis." (PMID 20976175, 2010). "E2F2 interacts with certain elements in the E2F1 promoter and both genes are involved in DNA replication and repair, cytokinesis, and tumor development." (PMID 20422009, 2010). "From immunohistochemistry staining, we found E2F1 expression was significantly lower in PXR-HT29 tumours compared with Vector-HT29 tumours." (PMID 20531417, 2010). "E2F1 expression remained unchanged, in contrast to previous findings in vitro, demonstrating the potential importance of the orthotopic tumour microenvironment on cell responses to GLA treatment." (PMID 19292920, 2009). "For example, miR-15 and miR-16 induce apoptosis by targeting Bcl2. miRNAs from the miR-17-92 cluster modulate tumor formation and function as oncogenes by influencing the translation of E2F1 mRNA." (PMID 17894887, 2007). "The tumor suppressor pathway in which p73 appears to be a participant involves E2F1, JunB, p16, p19, p57kip2 and BRCA1." (PMID 17407586, 2007). "The tumor suppressor network in which p73 appears to be a participant involves E2F1, JunB, INK4a/p16, ARF/p19, p57kip2 and BRCA1." (PMID 17407586, 2007). "Intratumoral injection of a helper-dependent adenovirus vector expressing E2F1 plus drug treatment resulted in a significant reduction of tumor volume." (PMID 17407586, 2007). "E2F1, which regulates the G1/S phase transition and has tumor suppressor properties, is increased in 12.2, consistent with our results from cell cycle analysis." (PMID 16083501, 2005). "Thus, utilizing distinct E2F1 activity acting on tumor suppressor promoter elements, such as EREA and ERE73, would represent a universal means to specifically induce gene expression in cancer cells while preserving normal growing cells." (PMID 41511373, 2026). "Moreover, E2F1 AS activity was evident as cells progress through the cell cycle and during the DNA damage response, and apparent in tumour models." (PMID 41614303, 2026). "Moreover, transcription factor activity analysis revealed elevated activity of several transcription factors, such as ARID2, E2F1, E2F4, NFYB, and MYC, in the RRhighepi group, all of which are closely associated with cell proliferation and tumor progression." (PMID 41424847, 2026). "Notably, analysis of E2F1 subcellular localization demonstrated a significantly higher nuclear-to-cytoplasmic ratio in tumor tissues relative to normal tissues (P < 0.001), suggesting transcriptional activation of E2F1 in GC." (PMID 41484982, 2026). "Besides cardinal ramifications for the cell cycle inhibition, CDK4/6 inhibitors have anti-tumor immunity-promoting effects which are derived from the inhibition of E2F1." (PMID 40699853, 2025). "Additionally, we observed that NCAPH-KD combined with these inhibitors resulted in a substantial reduction in the expression of NCAPH, E2F1, and Ki67 in the xenografted tumor tissues when compared to single treatments with Eve or Flav." (PMID 39991770, 2025). "In this study, we show that CTL-mediated immune pressure confers resistance to ferroptosis in tumor cells through transcriptional induction of HMGCR by E2F1, thereby could contribute to refractory phenotypes to T cell-based therapies." (PMID 41339438, 2025). "Moreover, transcription factor activity inference revealed the subcluster-specific expression of regulators such as FOXC1 and E2F1, highlighting the central role of transcriptional regulatory networks in shaping tumor phenotypes." (PMID 40496864, 2025).
tumor (continued). "E2F1 suppresses malignant tumor phenotypes by modulating cellular senescence." (PMID 41050059, 2025). "In addition, E2F1 inhibition in regulatory T cells down-regulates their activity allowing for increased unhindered anti-tumor effect of cytotoxic T cells." (PMID 40699853, 2025). "GNL3L promotes S phase progress and tumor cell proliferation by regulating the Rb‐E2F1 pathway." (PMID 40856423, 2025). "Similarly, E2F1 functions as a mediator of cell proliferation, migration, and survival pathways, highlighting its role in enabling tumor growth and metastatic potential." (PMID 40227503, 2025). "As E2F1-HMGCR is critical for ferroptosis-resistance of immune-refractory tumor cells, we reasoned that pharmacological inhibition of HMGCR might be an effective strategy for targeting immune-refractory tumor cells that highly express E2F1." (PMID 41339438, 2025). "Furthermore, adenoviral gene transfer of E2F1 in melanoma xenografts on nude mice led to significant enhancement of tumor response to topoisomerase II inhibitors." (PMID 40517236, 2025). "The transcription factor network of C3 MKl67+ tumor cells was mainly composed of E2F1, E2F2, etc.." (PMID 40230840, 2025). "Similarly, CCK-8 assay results demonstrated that tumor cell viability was significantly reduced following E2F1 overexpression, while E2F1 downregulation significantly increased tumor cell viability (p < 0.05)." (PMID 41050059, 2025). "However, E2F1 activation also induces apoptosis as a fail-safe mechanism for limiting tumor formation when E2F1 is dysregulated." (PMID 40517236, 2025). "We observed a stepwise increase in both E2F1 expression and proportion of E2F1+ cells from P0 to P3 cells, suggesting that E2F1 upregulation in P3 tumor cells results from the immune pressure–driven enrichment of pre-existing E2F1+ tumor cells during immunotherapy." (PMID 41339438, 2025). "In addition, E2F1 silencing suppressed the formation of capillary-like structures of HUVECs, suggesting the inhibition of tumor angiogenesis." (PMID 40221814, 2025). "The transcription factor E2F1 interferes with cell cycle regulation, resulting in tumor growth." (PMID 40225855, 2025). "E2F1 overexpression in glioma induces apoptosis and tumor suppression." (PMID 40517236, 2025). "E2F1, a pivotal transcription factor regulating diverse cellular processes such as proliferation, differentiation, migration, and metabolism, exhibits dual oncogenic and tumor-suppressive roles in cancer progression." (PMID 40830893, 2025). "To further investigate the impact of E2F1 on tumor progression, we conducted cell experiments." (PMID 41050059, 2025). "Among these, E2F1 is the first member of the E2Fs to be discovered that could bind both to Rb to exhibit tumor-suppressive effects, and induce tumorigenesis, drug resistance, and other adverse outcomes through its role as a transcriptional activator." (PMID 40886002, 2025). "In light of this, our current study suggests that immune pressure imposed by immunotherapy drives the selective enrichment of pre-existing E2F1+ tumor cells within the parental population, which in turn upregulate HMGCR expression and promote ferroptosis resistance." (PMID 41339438, 2025). "Interestingly, a hypophosphorylation of Rb and an accumulation of E2F1-Rb complex was also observed during HSV-1 infection of tumor cells, so that an initiated cell cycle can be blocked afterward." (PMID 38793657, 2024). "However, if exogenous human SPP1 protein is added, the expression of proliferation‐related genes (UBE2C, E2F1) in the co‐cultured tumor cells increases." (PMID 39716897, 2024).
tumor (continued). "Thus, elucidation of the mechanism by which E2F1 exerts selective transcriptional regulation of tumor suppressor genes is crucial to understanding the molecular basis of tumor suppression." (PMID 39595534, 2024). "Previous studies indicated that E2F1 acted as a tumor-promoting factor." (PMID 38783241, 2024). "E2F1 knockdown severely reduced these alterations in gene expression in both cell types to 1,462 (CD4+) and 1,708 (SK-Mel-47 E2F1-KD) DEGs, respectively, underlining the regulatory role of E2F1 in the crosstalk between tumor and immune cells." (PMID 39544930, 2024). "Herein we showed that DDX5 contributes to the tumor suppressive functions of deregulated E2F1." (PMID 39769018, 2024). "The results indicated that the A genotype of the rs35301225 SNP in miR-34a may act as a tumor suppressor by downregulating the oncogenic gene E2F Transcription Factor 1 (E2F1)." (PMID 39684686, 2024). "Similarly, lncRNA APUE countered the inhibitory effect of miR-20b on E2F1, leading to increased E2F1 levels that foster cell cycle progression and tumor growth." (PMID 38357004, 2024). "E2F1 interacts with and is inhibited by the retinoblastoma (RB) protein, a key tumor suppressor." (PMID 38344207, 2024). "Surprisedly, in all 31 cancer types in TCGA except low‐grade glioma (LGG), EXO1 and E2F1 were consistently upregulated in tumor samples compared to normal samples, and the upregulation of expression of these two genes was statistically significant in 20 of these cancer types." (PMID 38544480, 2024). "However, E2F1 also plays crucial roles in tumor suppression by activating tumor suppressor genes, which mediate apoptosis or cellular senescence." (PMID 39769018, 2024). "Dysregulated E2F1 activity, driven by genetic and molecular alterations such as mutations in the RB1 gene, plays a pivotal role in disease development by promoting uncontrolled cell proliferation and tumor formation." (PMID 39000021, 2024). "PDK4 level is regulated by E2F1 and influences tumor metabolism." (PMID 38371373, 2024). "E2F1 can function as both a tumor suppressor and an oncogene under different conditions." (PMID 38945955, 2024). "Moreover, PARP1 mediates the activity of the E2F1 transcription factor and affects cell cycle progression in embryonic development and tumor growth." (PMID 38481797, 2024). "Additionally, ATAC‐seq and gene array analyses have further uncovered that CLF amplifies the anti‐tumour capacity of tumour‐specific CD8+ T cells through the upregulation of E2F1‐induced Tcf7 promoter activation." (PMID 38965409, 2024). "We thus analyzed the effects of DDX5 on the tumor suppressive functions of E2F1." (PMID 39769018, 2024). "The expression level of E2F1 is upregulated in HCC compared to adjacent non-tumor tissue." (PMID 38792899, 2024). "Furthermore, analysis of E2F1 expression in 50 matched tumor and normal pairs demonstrated that E2F1 was significantly increased in tumor." (PMID 38403291, 2024). "However, the reduced arginine methylation of E2F-1 by PRMT5 in tumor cells stabilizes E2F-1, subsequently leading to apoptosis and tumorigenesis." (PMID 38911125, 2024). "In GC, E2F1 is highly upregulated and positively correlated with tumor malignancies." (PMID 39613162, 2024). "Myc induces E2F1, and in turn, E2F1 can induce Myc, so it could be possible that this positive feedback loop is also involved in NC tumor cells." (PMID 38793657, 2024). "The transcription factor E2F1 is a key driver of tumor evolution and metastasis." (PMID 39544930, 2024). "Lowering E2F1 expression or blocking the deleterious E2F1-STAT3/IL-6 axis to modulate the tumor secretome could therefore improve antitumor responses and reduce adverse effects when interleukins and ICIs are used in combination." (PMID 39544930, 2024).
tumor (continued). "Some of these tumours were associated with amplification or overexpression of CCNE1, as we characterized it in MPM_31 and MPM_34 cell lines; and/or with high transcript levels of E2F1, or E2F3 in the peculiar M631PT patient in Bueno's cohort." (PMID 36453028, 2024). "As a transcription factor, E2F1 is essential for tumor growth and metastasis." (PMID 36973424, 2023). "Furthermore, the correlation between the expression of the selected miR-1246 and miR-150-5p (with the lowest FDR value) in serum, and that of CCND1 and E2F1 was analysed in tumour tissue." (PMID 37935712, 2023). "KAT2A was highly expressed in non-small-cell radiation-induced lung cancer and may promote tumor progression by upregulating E2F1 and cyclin d1." (PMID 38058677, 2023). "Another study had suggested that E2F1 induced the senescence of ccRCC tumor cells via p27." (PMID 37077419, 2023). "Since IRF3, a tumor suppressor, and E2F1 and NR2C2, cancer promoters, have been reported to be important in cancer, investigation of the action of KIAA1324 in the regulation of these target genes is essential for understanding KIAA1324-related cancer development deeply." (PMID 37612293, 2023). "Moreover, VCN-01 harbours E2F1 promoters in the E1A region to increase viral replication in tumour cells." (PMID 37031291, 2023). "E2F1, an E2F transcription factor family member, participates in tumor development." (PMID 37160894, 2023). "Thus, KDM4A-AS1 overexpression overturned the alleviated effects of E2F1 silencing on tumor formation in vivo through PI3K/AKT signaling pathway." (PMID 36973424, 2023). "Plenty of studies have reported the tumor-promoting effect of E2F1." (PMID 36864456, 2023). "Activation of AMPK has up-regulated SLC7A2 expression and enhanced the sensitivity of NSCLC cells to anti-tumor drugs, which could be attributed to E2F1’s regulation." (PMID 36639771, 2023). "E2F1 is a prognostic marker in a variety of cancers, because E2F1 is involved in multiple regulatory pathways, which also the reason for its elevated expression in the tumor micro-environment." (PMID 37277745, 2023). "Consistent with in vitro results, E2F1 knockdown significantly delayed GC tumor growth." (PMID 35440106, 2022). "LncRNA Lnc‐APUE promotes tumor growth by regulating miR‐20b/E2F1 axis in HCC." (PMID 35293026, 2022). "Immunohistochemical analysis indicated down-regulation of E2F1 and Ki67 in the tumor tissues." (PMID 35152841, 2022). "Interestingly, CDCA7 is a DNA-binding protein and regulates the gene expression of the tumour-promoting effect of c-Myc and E2F1." (PMID 35167614, 2022). "Thus, in HPV-associated tumours, a predominance of mutations in the PI3CA gene and amplifications in the E2F1 gene has been demonstrated." (PMID 35954497, 2022). "Therefore, E2F1 serves as a key regulatory factor to affect tumor progression and an attractive target for cancer treatment." (PMID 35440106, 2022).
tumor (continued). "The results presented here showed a correlation of E2F-1 with the resistance of tumor cells to DDP; thus, we speculated that E2F-1 inhibition may be a potential target to reverse the DDP resistance of NPC cells." (PMID 35303867, 2022). "The functional approach of E2F1 indicated that E2F1 promoted GC cell proliferation, G1/S transition and suppressed GC cell apoptosis and DNA damage recognition foci accumulation in vitro and accelerated GC tumor growth in vivo." (PMID 35440106, 2022). "Restoration of E2F1 weakened the tumor-inhibitory effect of miR-532." (PMID 35440106, 2022). "Altogether, these results confirmed that the CHREBP/cyclin D1 axis could regulate GC progression via the Rb/E2F1 pathway, the activation of which has been elaborated to promote G1/S transition and enhance tumor cells proliferation." (PMID 35768405, 2022). "Conversely, the let-7 family, miR-34a, miR-145, and miR-29 targets are regarded as tumor suppressors and can inhibit tumor formation, proliferation, migration, spread, and angiogenesis by targeting many oncogenic transcription factors, including E2F1, K-RAS and c-MYC." (PMID 36532760, 2022). "More importantly, E2F-1 was found to affect the sensitivity of tumor cells to DDP." (PMID 35303867, 2022). "As for the mechanism, it was demonstrated that NLE1 may execute its tumor-regulating function through activating E2F1-mediated transcription of CDK1, and PI3K/Akt signaling pathway was also supposed as a downstream of NLE1 in the regulation of NSCLC." (PMID 36818671, 2022). "In addition, we further validated the inhibitory effects of E2F1 knockout on PTC tumor growth in vivo, as evidenced by decreased Ki67 positive expression." (PMID 35592867, 2022). "However, the newly evidence indicate that this E2F1 is aberrantly up-regulated in late-stage tumors and can promote tumor development and progression via a cell context-dependent loss of its death-inducing function." (PMID 36034466, 2022). "Collectively, these results suggest that SETD7 may have a tumour-promoting role in HCC by stimulating the cell cycle through E2F-1 stabilisation and possibly also by enhancing migration and metastasis." (PMID 35326563, 2022). "Functionally, E2F1, as a cell cycle-specific transcription factor (TF), has been reported to be highly expressed in a variety of tumors, and mainly participated in regulating tumor cell proliferation." (PMID 36434634, 2022). "Therefore, it is possible that the observed downregulation of E2F target gene pathway is reflecting the downregulation of E2F1-related pathways, impairing apoptosis in the tumor." (PMID 35562768, 2022). "Moreover, E2F1 plays a role in regulating cancer characteristics such as tumor proliferation, apoptosis, metastasis, and metabolism processes." (PMID 35186166, 2022). "Furthermore, elevated E2F1–3 and E2F5 expression levels were associated with a higher Gleason score (GS), advanced tumor stage, and metastasis." (PMID 35531101, 2022). "E2F1 is a representative transcription factor that plays vital roles in tumor progression." (PMID 35440106, 2022). "Additionally, IHC staining showed decreased expression of Ki-67, cyclin D1, cyclin E1, and E2F1 in sh-CENPU-treated Huh-7 xenograft tumours." (PMID 35844791, 2022). "Furthermore, restoration of E2F1 expression in GBM cells effectively rescued the tumor-suppressive effect of miR-1258." (PMID 34079762, 2021). "Specifically, E2F1 promotes tumor malignancy and correlates with TNM stage in ccRCC." (PMID 33468140, 2021). "Moreover, it is well acknowledged that E2F1 can promote tumor carcinogenesis, development, and progression via the facilitation of cell proliferation and migration." (PMID 33816295, 2021).